AGTR1 (angiotensin II receptor type 1)
Diseases named in the same sentence as AGTR1 in open-access papers (continued):
Sharing a sentence is not in itself a finding about the gene and the disease.
bladder cancer (7 papers, 2011 to 2026). "Here, we investigated the contribution of AngII type 1 receptor (AGTR1) to bladder cancer progression and assessed the therapeutic potential of the ARB losartan (LOS)." (PMID 41549123, 2026). "In AGTR1-overexpressing T24 bladder cancer cells, AngII promoted invasion and migration and upregulated neuronal nitric oxide synthase, without affecting proliferation." (PMID 41549123, 2026). "In conclusion, our findings highlight the crucial role of AGTR1 in bladder cancer and support the repositioning of ARBs, such as LOS, as therapeutics for AGTR1-upregulated bladder cancer, while underscoring the importance of AGTR1 stratification for future clinical evaluation." (PMID 41549123, 2026).
breast tumor (7 papers, 2006 to 2023). "AGTR1 over-expression was observed to be approximately 100-fold higher in 10-20% of breast tumours, specifically in ER+ve/HER2−ve primary tumours, positively correlating with poor prognosis and chemoresistance." (PMID 28416734, 2017).
cognitive decline (7 papers, 2018 to 2025). "A recent study showed higher Ang-II type 1 receptor (AGTR1) levels in the FCx in relation to cognitive decline and elevated markers of disease pathology, including raised levels of oxidative stress, inflammation, Aβ, and tau." (PMID 35396835, 2022).
colon cancer (7 papers, 2013 to 2023). "Accumulating epigenetic data have implicated that colon cancer is a deadly disease attributed to interactions between multiple genes, such as cumulative mutations and aberrant methylation of certain genes, such as M2 isoform of pyruvate kinase (PKM2) and angiotensin II receptor, type 1 (AGTR1)." (PMID 29069781, 2017).
endometrial cancer (7 papers, 2006 to 2025). Primary or metastatic malignant neoplasm involving the endometrium (mucous membrane that lines the endometrial cavity). "We also showed that the mRNA expression of AGTR1 and ACE were significantly higher in endometrial cancer tissue, further indicating the potential for increased Ang II/AT1R signalling in endometrial cancer." (PMID 41303450, 2025). "A study of 30 endometrial cancer samples showed that high expression of ATP6AP2, AGTR1, and ACE1 in the RAS was associated with the spread of endometrial cancer." (PMID 39257906, 2024). "The increased expression of AGTR1, ATP6AP2, and ACE1, crucial components of the RAS’s pro-angiogenic/proliferative arm, raises the possibility that the RAS is involved in the development and progression of endometrial cancer." (PMID 37869088, 2023).
lymph node metastasis (7 papers, 2012 to 2024). "High expression of AGTR1 has been found to be linked with less lymph node metastasis and mesenchymal-epithelial transition factor (MET) mutations." (PMID 39450258, 2024). "AGTR1 is upregulated in most of the samples with high immune and stromal scores and promotes lymph node metastasis in BRCA27." (PMID 36869083, 2023). "Apart from these factors, the angiotensin II (Ang II) type I receptor (AGTR1) may also affect lymph node metastasis." (PMID 31219799, 2019). "Then, we defined the oncogenic role of AGTR1 in lymph node metastasis invivo." (PMID 31219799, 2019). "Therefore, our data strongly suggest that blocking AGTR1 reduces lymph node metastasis invivo and that this effect is likely mediated via CXCR4/SDF-1α." (PMID 31219799, 2019). "Therefore, higher expression of AGTR1 protein significantly correlated with lymph node metastasis (P<0.05) but not with age, histological grade or tumor size." (PMID 31219799, 2019).
renal cell carcinoma (7 papers, 2014 to 2025). "However, there was a study which determined the gene-diet interactions involving the AGTR1 gene (rs5186) SNP with sodium, potassium, and fluid intakes on renal cell cancer risk." (PMID 28792482, 2017). "Polymorphisms in genes of the renin-angiotensin-aldosterone system (AGTR1 and AGT) influenced renal cell cancer susceptibility." (PMID 26537097, 2015).
type 1 diabetes (7 papers, 2014 to 2025). "This study was performed to examine clinical and laboratory differences between adolescents with type 1 diabetes with and without microalbuminuria and the distribution of the ACE, AGTR1, and MTHFR gene polymorphisms." (PMID 39446857, 2024).
Arthritis (6 papers, 2012 to 2022). Inflammation of a joint. "It has been shown that losartan ameliorates adjuvant-induced arthritis in rats via down-regulation of AGTR1 and up-regulation of AGT2R expression." (PMID 35372645, 2022).
endometriosis (6 papers, 2019 to 2025). The growth of functional endometrial tissue in anatomic sites outside the uterine body. "The pathogenesis of endometriosis is based on multiple data sets of genes which mainly include the AGTR1 gene responsible for encoding angiotensin II receptor type 1 (AT1R)." (PMID 37869088, 2023). "In order to further validate the expression of AGTR1 in EC and EU and to evaluate the diagnostic value of CXCL12, PTGER3, and AGTR1 in endometriosis, we need to increase the sample size." (PMID 36524127, 2022). "Various sets of genes involved in the pathogenesis of endometriosis include the AGTR1 gene." (PMID 37869088, 2023). "Moreover, oestrogen was found to regulate the expression levels of AGTR1 in stromal cells, thereby, possibly contributing to the pathogenesis of endometriosis." (PMID 35628346, 2022). "This suggests that AGTR1 could be a potential therapeutic target for EM.However, in our clinical sample validation, the expression level of ATGR1 in EC was lower than in EU and normal endometrium, which could be attributed to endometriosis heterogeneity and the small sample size." (PMID 36524127, 2022).
nonalcoholic fatty liver disease (6 papers, 2013 to 2023). "Moreover, AGTR1 rs3772622 polymorphism increases the risk of CHD in Northern Han Chinese patients with non-alcoholic fatty liver disease (NAFLD)." (PMID 31538912, 2020). "Angiotensin II type 1 receptor (AGTR1) has been reported to play a fibrogenic role in non-alcoholic fatty liver disease (NAFLD)." (PMID 23484035, 2013).
osteosarcoma (6 papers, 2017 to 2024). A usually aggressive malignant bone-forming mesenchymal neoplasm, predominantly affecting adolescents and young adults. "High levels of miR-1248 and its target gene AGTR1 were reported in osteosarcoma (OS) and associated with chemoresistance of OS cells and poor survival of patients." (PMID 35715818, 2022).
anemia (5 papers, 2012 to 2025). A reduction in the number of red blood cells, the amount of hemoglobin, and/or the volume of packed red blood cells. "Moreover, deletional mutations in the ACE and AGTR1 genes encoding the human ACE and AT1R, respectively, lead to anemia in humans demonstrating a conserved role." (PMID 39869503, 2025).
Autoimmunity (5 papers, 2021 to 2025). The occurrence of an immune reaction against the organism's own cells or tissues. "In this study, we aimed to determine the role of complement C3 in the development of a recently described SSc mouse model based on autoimmunity to angiotensin II receptor type 1 (AT1R)." (PMID 39737181, 2024).
glioblastoma (5 papers, 2021 to 2026). The most malignant astrocytic tumor (WHO grade IV). "AGTR1 expression in terms of mRNA and protein content is significantly upregulated in both U-87 MG and T98G glioblastoma cell lines, displaying different gene mutations compared to normal human glial cells (SVG p12)." (PMID 34572782, 2021). "The expression of RAS receptors (AGTR1, AGTR2, and ATP6AP2) has been demonstrated on the glioblastoma microvasculature, and the inhibition of AGTR1 or AGTR2 reduced glioblastoma cell growth in vitro and in vivo." (PMID 38607073, 2024). "Ang II/AGTR1 signaling pathway appeared more active in both glioblastoma cell lines displaying an enhanced phosphorylated status of STAT3 and MAPK in basal condition, which was further increased after Ang II short exposure." (PMID 34572782, 2021). "This highlights the intrinsic capability of Ang II/AGTR1 signaling in modulating intracellular aromatase activity sustaining glioblastoma cell growth." (PMID 34572782, 2021). "The combined expression of RAS receptors (ATP6AP2, AGTR1, and AGTR2) was positively associated with gene pathways involved in hypoxia, microvasculature, stem cell plasticity, and the molecular characterisation of glioblastoma subtypes." (PMID 38607073, 2024). "The glioblastoma cell lines U-87 MG and T98G overexpresses Angiotensin II (Ang II)/Angiotensin II type I receptor (AGTR1) signaling, which enhances in vitro and in vivo local estrogen production through a direct up-regulation of the aromatase gene promoters p I.f and p I.4." (PMID 34572782, 2021). "The combination of TMZ + RT resulted in a slight but significant increase in the expression of ATP6AP2, AGTR1, and ACE, while AGT and the lowly expressed AGTR2 and REN remained unchanged across all 12 glioblastoma cell lines." (PMID 38607073, 2024). "When compared to LGG cases, ATP6AP2, AGTR1, and ACE were significantly higher in expression in glioblastomas, with AGTR1 showing the highest change in expression (5.7-fold higher)." (PMID 38607073, 2024). "Progression-free survival (PFS) and overall survival (OS) were compared across TCGA glioblastoma cases, stratified from high and low expression of ATP6AP2, AGTR1, AGTR2, ACE, AGT, and REN genes." (PMID 38607073, 2024). "Although this study did not explore the targeting of RAS components, inhibition of RAS receptors such as AGTR1, AGTR2, and ATP6AP2 have been demonstrated to reduce glioblastoma cell growth, proliferation, and/or angiogenesis." (PMID 38607073, 2024). "The majority of RAS genes (ATP6AP2, AGTR1, AGTR2, and ACE) in our study were highly expressed in glioblastomas compared to LGGs." (PMID 38607073, 2024). "In patient-derived glioblastoma cell lines, ATP6AP2 and AGTR1 were upregulated after chemoradiotherapy and correlated with an increase in HIF1A expression." (PMID 38607073, 2024). "Baseline expressions of RAS genes were relatively similar to the TCGA glioblastoma cohort, where REN and AGTR2 were very lowly expressed while ATP6AP2, AGTR1, ACE, and AGT were consistently expressed." (PMID 38607073, 2024). "The baseline mRNA expression of RAS genes (ATP6AP2, AGTR1, AGTR2, AGT, ACE, and REN) were explored in 12 patient-derived glioblastoma cell lines." (PMID 38607073, 2024). "The majority of genes (ATP6AP2, AGTR1, ACE, and AGT) were consistently expressed in glioblastoma cases, with the exception of AGTR2 and REN." (PMID 38607073, 2024). "In cases of glioblastoma within the TCGA, ATP6AP2, AGTR1, ACE, and AGT had consistent expressions across samples, while AGTR2 and REN were lowly expressed." (PMID 38607073, 2024). "We, thus, examined the relationship of RAS receptors (ATP6AP2, AGTR1, and AGTR2) with TME expression within TCGA glioblastoma samples." (PMID 38607073, 2024). "As ATP6AP2, AGTR1, and AGTR2 are the main receptors in the RAS; this suggests that glioblastomas have a greater capacity to utilise this pathway for their survival." (PMID 38607073, 2024).
glioblastoma (continued). "Here, we investigated the gene expression of RAS components (ATP6AP2, AGTR1, AGTR2, ACE, AGT, and REN) in glioblastoma patient samples from The Cancer Genome Atlas (TCGA) and their association with survival outcomes and the expression of TME pathways." (PMID 38607073, 2024). "The level of expression of ATP6AP2, AGTR1, AGTR2, and ACE genes in glioblastomas was similar to that observed in a range of other solid tumours and haematological cancers." (PMID 38607073, 2024). "We studied the expression of RAS-related genes (ATP6AP2, AGTR1, AGTR2, ACE, AGT, and REN) in The Cancer Genome Atlas (TCGA) glioblastoma cohort, their relationship to patient survival, and association with tumour microenvironment pathways." (PMID 38607073, 2024). "ATP6AP2, AGTR1, AGTR2, AGT, and ACE had low frequencies of CNAs (<1%) in glioblastomas; however, REN was altered in 6% of glioblastoma cases." (PMID 38607073, 2024). "AGTR1 has been recently reported to be significantly associated with poorer PFS and/or OS in a TCGA glioblastoma cohort; however, the authors did not perform multivariate analysis." (PMID 38607073, 2024). "A further study on the miRNA-AGTR1 relationship and the molecular mechanism of AGTR1-mediated signaling showed that miR-155-5p depresses EMT process and anchorage-independent growth by attenuating the activity of NF-κB via targeting AGTR1 in glioblastoma." (PMID 33435156, 2021). "The majority of glioblastoma cases expressed ATP6AP2, AGTR1, ACE, and AGT but not AGTR2 and REN." (PMID 38607073, 2024).
IgA nephropathy (5 papers, 2019 to 2025). "Sparsentan, a dual-acting antagonist for both the angiotensin II receptor type 1 and the endothelin receptor type A, has emerged as a promising therapeutic agent for the treatment of IgA nephropathy (IgAN)." (PMID 39872637, 2025). "One meta-analysis published in 201455 assessed AGTR1 in individuals with CKD, ESRD, IgA nephropathy or vesicoureteral reflux." (PMID 31048445, 2019).
osteoarthritis (5 papers, 2018 to 2026). A noninflammatory degenerative joint disease occurring chiefly in older persons, characterized by degeneration of the articular cartilage, hypertrophy of bone at the margins and changes in the synovial membrane. "Angiotensin II (Ang II), by activating the angiotensin II type 1 receptor (AGTR1), leads to pathological changes in the knee joints of experimental osteoarthritis mice, such as articular cartilage degradation, subchondral bone sclerosis, inflammation, and synovial damage." (PMID 37853066, 2023).
renal carcinoma (5 papers, 2010 to 2023). A carcinoma arising from the epithelium of the renal parenchyma or the renal pelvis. "Two SNPs in AGTR1 might be a candidate pathway in renal cancer etiology." (PMID 26537097, 2015).
cardiac arrhythmia (4 papers, 2004 to 2023). Any disturbances of the normal rhythmic beating of the heart or MYOCARDIAL CONTRACTION. "An increase in AGTR1 staining has been reported in the fibrotic regions surrounding the bronchioles in chronic obstructive pulmonary disease." (PMID 15571627, 2004).
Hyperkalemia (4 papers, 2015 to 2022). An abnormally increased potassium concentration in the blood. "And how should hyperkalemia, salt-wasting and hypotension be treated in a patient with loss of AGTR1 function?" (PMID 33768328, 2021).
Hypokalemia (4 papers, 2015 to 2023). An abnormally decreased potassium concentration in the blood. "This stimulates angiotensin II receptor type 1 (AT1R) which further leads to hypokalemia, causing lung and cardiovascular injury." (PMID 37656879, 2023).
invasive breast carcinoma (4 papers, 2014 to 2022). A carcinoma that infiltrates the breast parenchyma. "The stage of breast invasive carcinoma was correlated with AGTR1 and ADD1." (PMID 35513851, 2022).
liver cancer (4 papers, 2017 to 2026). An epithelial or non-epithelial malignant neoplasm that arises from the liver. "The AGTR1 abundance in liver cancer and adrenal cancer may provide a clue for tumor origin." (PMID 34671200, 2021).
lung adenocarcinoma (4 papers, 2022 to 2025). A carcinoma that arises from the lung and is characterized by the presence of malignant glandular epithelial cells. "In contrast, AGTR1 is a potential cancer suppressor gene, and the high AGTR1 expression in lung adenocarcinoma promotes the formation of an antitumor microenvironment." (PMID 36983741, 2023).
periodontitis (4 papers, 2015 to 2025). An acute or chronic inflammatory process that affects the tissues that surround and support the teeth. "With regard to down-regulated genes, there was no gene common to all four diseases, although one gene, angiotensin II type I receptor (AGTR1), was down-regulated in periodontitis, CVD, and RA." (PMID 26686060, 2015).
pulmonary edema (4 papers, 2016 to 2022). Accumulation of fluid in the lung tissues causing disturbance of the gas exchange that may lead to respiratory failure. "Previous studies demonstrated that Angiotensin II Receptor 1 (AGTR1) may play an important role in the development of high-altitude pulmonary edema." (PMID 27732943, 2016).
rheumatoid arthritis (4 papers, 2013 to 2022). A chronic, systemic autoimmune disorder characterized by inflammation in the synovial membranes and articular surfaces. "Notably, it was reported that AGTR1 expression was detected not only in articular chondrocytes derived from OA and rheumatoid arthritis (RA) patients but also in normal chondrocytes, whereas AGTR2 expression was detected in diseased chondrocytes only." (PMID 34502113, 2021). "Oral administration of losartan has also been shown to have beneficial effects in the musculoskeletal system such as in rheumatoid arthritis (RA) via up-regulation of angiotensin II receptor type 2 (AGT2R) and down-regulation of angiotensin II receptor type 1 (AGTR1)." (PMID 35372645, 2022).
blood pressure (3 papers, 2021). "More consistent, an upregulation of angiotensin II was reported in vascular tissue and cells exposed to BPA and the antagonist of angiotensin II receptor type 1 (AT1) reversed the BPA-induced high blood pressure." (PMID 33912069, 2021).
renal tubular dysgenesis (3 papers, 2021 to 2024). "Genetic loss of function of AGT (angiotensinogen), REN (renin), ACE (angiotensin-converting enzyme), or AGTR1 (type-1 angiotensin II receptor) leads to renal tubular dysgenesis (RTD)." (PMID 33768328, 2021).
respiratory failure (3 papers, 2020 to 2025). The significant impairment of gas exchange within the lungs resulting in hypoxia, hypercarbia, or both, to the extent that organ tissue perfusion is severely compromised. "The impact of this gene variant on ROP may be more substantial in newborns with respiratory failure and in carriers of the AGTR1 rs5186C allele." (PMID 40175432, 2025).
autonomic dysfunction (2 papers, 2014 to 2017). "Consistent with the inversion of these interactions, the temporal patterns of brainstem Tnf and Agtr1 expression was inverted in the control phenotype relative to that of autonomic dysfunction." (PMID 28732007, 2017).
cholangiocarcinoma (2 papers, 2017 to 2020). A carcinoma that arises from the intrahepatic biliary tree (intrahepatic cholangiocarcinoma) or from the junction, or adjacent to the junction, of the right and left hepatic ducts (hilar cholangiocarcinoma). "Further bioinformatics analysis using the cholangiocarcinoma (TCGA, PanCancer Atlas) dataset indicated a significant inverse association between AGTR1 methylation and AGTR1 gene expression (r = -0.595, p = 1.29E-04)." (PMID 31538912, 2020). "Further data mining analysis using the cholangiocarcinoma (TCGA, PanCancer Atlas) data indicated an inverse association between AGTR1 methylation and AGTR1 expression (r = -0.595, p = 1.29E-04)." (PMID 31538912, 2020).
coagulopathy (2 papers, 2022 to 2023). "In this randomized controlled experimental medicine study, we tested the hypothesis that COVID‐19‐associated coagulopathy is partly driven by RAAS dysregulation by measuring the response on D‐dimer of a biased agonist at the AGTR1 in hospitalized COVID‐19 patients." (PMID 36437688, 2023).
coronary atherosclerosis (2 papers, 2012 to 2024). Atherosclerosis of the coronary vasculature. "In terms of pathogenesis, the AT1 receptor may be overexpressed in carriers of the AGTR1 A1166C variant, leading to increased adverse effects of angiotensin II on coronary atherosclerosis." (PMID 38635772, 2024). "The results of other studies are conflicting regarding the effect of AGTR1 A1166C variants on coronary artery lesions due to differences in genotype distributions across countries and races, and the frequency of environmental factors affecting coronary atherosclerosis." (PMID 38635772, 2024).